U3 (Small nucleolar RNA U3 )
Gene: Small nucleolar RNA gene on chromosome 18 (26,689,316 to 26,689,529, reverse strand). Ensembl gene ENSG00000275900.
Gene Ontology:
Biological process: RNA processing
Cellular component: nucleolus
Homologues: Orthologues: chimpanzee U3 (99% identical), macaque U3 (91% identical). Paralogues in human: U3 (78% identical), U3 (77% identical), SNORD3P1 (77% identical), SNORD3E (75% identical), SNORD3G (74% identical), U3 (74% identical), U3 (73% identical), U3 (72% identical), SNORD3H (72% identical), SNORD3D (71% identical), U3 (71% identical), U3 (70% identical), and 13 more.